BRCA1 (BRCA1 DNA repair associated)
Diseases named in the same sentence as BRCA1 in open-access papers (continued):
Sharing a sentence is not in itself a finding about the gene and the disease.
breast cancer (continued). "Women with documented pathogenic mutations in the breast cancer susceptibility genes BRCA1/2 and women with a history of thoracic radiation therapy are at especially high risk of breast cancer." (PMID 40177455, 2025). "Progesterone plays key roles in normal breast development and in certain subtypes of breast cancer, particularly those driven by BRCA1 mutations." (PMID 40243654, 2025). "Mutations in breast cancer susceptibility genes 1/2 (BRCA1/2) are strongly associated with a significantly higher risk of numerous cancers, including ovarian, breast, prostate, and pancreatic cancer." (PMID 40182045, 2025). "Inhibition of PARP‐1 leads to inadequate function of the DDR repair system and inhibits replication in breast cancer genes 1 and 2 (BRCA1/2) protein‐deficient cancer cells, a concept known as “synthetic lethality”." (PMID 39945311, 2025). "In breast cancer treatment, the detection of BRCA1/2 gene mutations is critically important, as it guides both therapeutic decisions and genetic counseling." (PMID 40065879, 2025). "Diagnoses prior to surgery included invasive ductal carcinoma (n = 8, 72.7%), ductal carcinoma in situ (n = 2, 18.2%), and genetic risk from a BRCA1 gene mutation with family history of breast cancer (n = 1, 9.1%)." (PMID 40806826, 2025). "Normal weight (vs. overweight) at menarche and at age 21 were significantly associated with older age of breast cancer onset among women with BRCA1 or BRCA2 mutations." (PMID 40523654, 2025). "Breast cancer ranks among the top causes of cancer-related deaths in women around the globe, with genetic mutations in the BRCA1 gene being a frequent cause of breast or ovarian cancer." (PMID 40904409, 2025). "This study included patients who were diagnosed with pathogenic BRCA1/2 variants either after developing breast cancer or based on family history, and therefore, selection bias in the dataset is inevitable." (PMID 40862027, 2025). "Among the non-modifiable factors, genetic mutations in the Breast Cancer Gene 1 and Breast Cancer Gene 2 (BRCA1 and BRCA2) are the most common alterations in breast cancer." (PMID 40417678, 2025). "Despite only 5% to 10% of breast cancer cases being inherited, approximately 55% to 65% of individuals with a BRCA1 gene mutation and 45% of those with a BRCA2 gene mutation develop breast cancer by the age of 70." (PMID 40427149, 2025). "Although effective therapies for BRCA1-deficient breast cancer are urgently needed, treatment options remain limited at present." (PMID 41208884, 2025). "In this review, we first give an overview of the contribution of BRCA1/2 gene mutations in breast cancer development." (PMID 40523654, 2025). "Question: How do germline BRCA1/2 mutations influence neoadjuvant chemotherapy response and survival outcomes in breast cancer patients?" (PMID 40405286, 2025). "In breast cancer, olaparib and talazoparib are approved for BRCA1/BRCA2-mutated, HER2-negative metastatic TNBC." (PMID 40864792, 2025). "In BRCA1-deficient murine breast cancer models, this phenotypic reprogramming was mediated by the activation of the stimulator of interferon genes (STING) pathway, which is an established driver of enhanced anti-tumour immune responses upon CDK4/6 inhibition." (PMID 41388212, 2025). "Based on mutation frequencies and cancer risk, the two most important susceptibility genes for breast cancer are BRCA1 and BRCA2." (PMID 40649769, 2025).
breast cancer (continued). "Since these mechanisms are also essential for effective tumor cytotoxicity, we explore tumor-specific effects, particularly in hereditary breast cancer linked to BRCA1 and BRCA2 mutations." (PMID 39621070, 2025). "Genomic instability in tumors is significantly increased due to endogenous and exogenous factors, such as breast cancer 1/breast cancer 2 (BRCA1/BRCA2) gene mutations and oxidative stress." (PMID 40444043, 2025). "Patients with BRCA1/2 mutations have a significantly higher lifetime risk of developing breast cancer and are more likely to experience bilateral breast cancer and an earlier onset of the disease." (PMID 40405286, 2025). "Beyond female breast and ovarian cancers, germline pathogenic variants in BRCA1 have also been associated with elevated risks of male breast cancer, pancreatic, and gastric cancers, and associations with colorectal and gallbladder cancers have been suggested." (PMID 41194282, 2025). "With this in mind, we undertook a systems-level characterization of acquired Olaparib resistance in MDAMB436 and HCC1428 breast cancer cells, which carry BRCA1 and BRCA2 mutations, respectively." (PMID 40669753, 2025). "BRCA1/2 are the most common genes related to breast cancer susceptibility, and germline BRCA mutations (gBRCAm) lead to hereditary breast cancer and/or ovarian cancer (HBOC) syndrome." (PMID 40994809, 2025). "Studies also showed that BRCA1 deficient breast cancers are derived from ERα+ luminal epithelial cells and go through luminal-basal transformation during tumorigenesis." (PMID 40157910, 2025). "The cumulative risk of breast cancer by age 70 was derived from the report of Beijing Municipal People’s Government and previous reports for general Chinese women and BRCA1/2 carriers, respectively." (PMID 40567951, 2025). "This study identified a homozygous missense variant (c.2312T > C:p.Leu771Ser) in the BRCA1 gene among breast cancer patients admitted at the INOR Cancer Hospital in Abbottabad, Pakistan." (PMID 40904409, 2025). "Breast cancer susceptibility genes 1 and 2 (BRCA1 and BRCA2) are two key tumor suppressor genes involved in this process." (PMID 40429877, 2025). "ZNF251 haploinsufficiency in BRCA1-mutated breast cancer reduces PARPi efficacy by restoring HR function." (PMID 40864792, 2025). "In this regard, it has been shown that approximately 57–80% of BRCA1-associated breast cancers are triple-negative in terms of their phenotype." (PMID 41249701, 2025). "With increased awareness and improved genetic testing, more individuals carrying the BRCA1/2 variants or other breast cancer-related pathogenic variants are being identified." (PMID 41083355, 2025). "Individuals with BRCA1 germline mutations are more susceptible to breast cancer, with up to 35% of newly diagnosed breast cancer patients harboring BRCA1 mutations." (PMID 39997609, 2025). "In contrast, mutations located in the 5′ and 3′ regions of the BRCA1 gene have been associated with relatively higher risks of breast cancer, and these regions are called the breast cancer cluster regions (BCCRs)." (PMID 41440233, 2025). "This study investigates hotspot mutations in exon 11 of the BRCA1 gene among Pakistani women diagnosed with breast cancer." (PMID 40904409, 2025). "Breast cancer is a multifaceted disease, influenced by various factors, including genetic mutations (e.g. BRCA1, BRCA2), hormonal influences, age, and gender." (PMID 40353126, 2025). "As mentioned, 1 in 10 women with breast cancer diagnosed under 40 years carry a BRCA1/2 mutation, and among these patients, a higher-than-expected pregnancy rate was observed (19% in 10 years)." (PMID 41002733, 2025).
breast cancer (continued). "Concerns regarding ipsilateral breast tumor recurrence (IBTR) and regional recurrence in patients with breast cancer with BRCA1 or BRCA2 pathogenic variants undergoing BCT still persist." (PMID 40366658, 2025). "Women with a BRCA1 mutation face a significantly increased lifetime risk of breast cancer, with estimates ranging from 60% to 72%, while those with a BRCA2 mutation have a high lifetime risk of 55% to 77%." (PMID 40941615, 2025). "BRCA1/2 gene mutations have been extensively studied in malignant tumors such as breast cancer and ovarian cancer, but are extremely rare in GIST." (PMID 40823097, 2025). "BARD1, a tumor suppressor in concert with the breast cancer susceptibility gene BRCA1, plays a significant role in BRCA1-driven tumor suppression." (PMID 40901482, 2025). "BRCA1/2 gene mutations are the most well-known defects in DNA repair and have been estimated to account for around 2.5% of breast cancer cases and approximately 30% of cases with a positive family history of breast or ovarian cancer." (PMID 40507226, 2025). "Individuals with BARD1 and BRCA1 germline pathogenic mutations have been found to have a higher incidence rates of aggressive breast cancer phenotypes, such as TNBCs, which are associated with higher rates of recurrence, progression, and mortality." (PMID 40805222, 2025). "The ASCO/ASTRO/SSO guidelines recommend offering CRRM for women with breast cancer carrying a BRCA1 or BRCA2 P/LP variant and who have been treated or are being treated with unilateral mastectomy." (PMID 39858629, 2025). "The usefulness of prophylactic surgery and surveillance for hereditary breast cancer in breast cancer patients with germline BRCA1 or BRCA2 variants has been demonstrated." (PMID 39831988, 2025). "The studied recurrent BRCA1/2 pathogenic variants were enriched in the cases (0.9%) but remained still individually rare and thus explain only a small proportion of breast cancer cases unselected for family history of cancer and age at disease onset." (PMID 40009290, 2025). "Women who have inherited germline mutations in BRCA1 or BRCA2 are at a significantly elevated lifetime risk of developing breast cancer, estimated at 80% and 72%, respectively." (PMID 39863726, 2025). "While high-penetrance mutations in BRCA1/2 account for a fraction of hereditary breast cancers, most disease risk arises from the cumulative effects of more frequent, low-penetrance alleles." (PMID 41301862, 2025). "A recent study evaluating second primary cancer risks in over 25,000 BRCA1 pathogenic variant carriers diagnosed with breast cancer found a significantly increased risk of CRC compared to population incidence rates." (PMID 41194282, 2025). "The identification of breast cancer susceptibility genes BRCA1/2, whose proteins are involved in DNA repair through homologous recombination, has shed light on some mechanisms behind sporadic and hereditary breast cancers." (PMID 39966355, 2025). "Genetic factors contribute to 5% to 10% of cases, and women with BRCA1 or BRCA2 mutations face a 50% to 85% lifetime risk of developing breast cancer." (PMID 39960903, 2025). "The lifetime risk of developing breast cancer is significantly higher among women with inherited risk factors for breast cancer, especially those with the BRCA1 and BRCA2 pathogenic variants." (PMID 41083355, 2025). "Expectedly, nine patients with ovarian cancer and one patient with breast cancer had a BRCA1 pathogenic variant." (PMID 41465149, 2025). "The transcription factor BRCA1 activates the DNA damage response, and a mutation of its gene has been detected in approximately half of hereditary breast cancer cases." (PMID 40001488, 2025). "TNBC constitutes approximately 15% to 20% of all diagnosed breast cancer cases, and is more commonly diagnosed in younger women, African-American women, and those with a breast cancer 1 (BRCA1) gene mutation." (PMID 40284417, 2025).
breast cancer (continued). "HRD in breast cancer is associated with germline and somatic mutations in BRCA1/2 tumor suppressor genes, BRCA1 promoter methylation, or mutations in other genes involved in homologous recombination such as RAD51C, RAD51D, PALB2, BRIP2, BARD1, ATM, and CHEK2." (PMID 40003864, 2025). "The interplay between BRCA1-mutated breast cancer and ncRNAs has recently garnered significant interest." (PMID 39997609, 2025). "This survey indicates that the tumors occurring in women with PJS seem to be slower growing, less likely to recur, and have better prognosis than tumors that are reported in other high-risk breast cancer groups, like BRCA1 and BRCA2 PV carriers." (PMID 40317347, 2025). "Although RRM is an effective method for reducing breast cancer risk in women with P/LP variants in BRCA1/2 genes, carriers should be informed of its impact on quality of life." (PMID 40445415, 2025). "Women with BRCA1 mutations are at an increased cumulative risk of breast cancer, ranging from 44% to 78%." (PMID 40940924, 2025). "This study presents a review of existing data on the impact of genetic modifiers on breast cancer risk among individuals carrying pathogenic variants in the BRCA1 and BRCA2 genes." (PMID 40296163, 2025). "Our findings suggest a second mechanism in which breast cancer cells, which are often deficient in the HR genes BRCA1/2, are killed due to synthetic lethality of raloxifene-induced inhibition of AOX1." (PMID 41372233, 2025). "Carriers of BRCA1 germline pathogenic variants have a significantly high lifetime risk of breast cancer – up to 72%, whereas BRCA2 carriers have a slightly lower but still a substantial risk of around 69%." (PMID 40390061, 2025). "In HR, the breast cancer susceptibility proteins BRCA1 and BRCA2 facilitate the loading of RAD51 onto ssDNA at the damage site, forming right-handed helical filaments on ssDNA." (PMID 40741921, 2025). "Most guidelines on breast cancer surveillance for BRCA1 and BRCA2 P/LP variant carriers recommend starting breast screening at 25 years or individualizing the screening according to family history if a breast cancer diagnosis before age 30 is present." (PMID 39858629, 2025). "In breast cancer prevention—especially among individuals harboring BRCA1/2 mutations—DNA vaccines hold promise by preemptively inducing immunity to tumor antigens." (PMID 40243654, 2025). "The collective findings of this in-depth characterization provide a strong rationale for further exploring immunotherapeutic strategies targeting BRCA1-associated breast cancer." (PMID 41208884, 2025). "In conclusion, our study employed PSM to evaluate the impact of BRCA1/2 mutations on pCR rates and survival outcomes in breast cancer." (PMID 40405286, 2025). "In patients carrying a BRCA1 mutation, the average cumulative risk of developing breast cancer by the age of 70 is approximately 65%, whereas the risk for ovarian cancer is around 39%." (PMID 40718262, 2025). "Take, for example, the BRCA1/2 genes, the intensely studied pair known as Breast Cancer Susceptibility Genes largely famous for their mutant germline variant responsible for familial cases of breast cancer." (PMID 40276264, 2025). "A combination treatment between platinum-containing drugs and a PARP inhibitor is one of the therapeutic strategies to improve their efficacy in BRCA1/2-deficient breast cancer cells." (PMID 41155174, 2025). "An illustrative human study focused on women with BRCA1 mutations (a high-risk group for breast cancer) found that the protective association between coffee intake and breast cancer incidence depended on CYP1A2 genotype." (PMID 40650030, 2025). "This prospective approach provides new insight into alternative treatments for breast cancers with BRCA1-associated TNBC." (PMID 41155174, 2025). "RR-BSO has previously been found to reduce the risk of breast cancer in female BRCA1/2 carriers by 50%, but the effect was questioned in other studies." (PMID 40974500, 2025).
breast cancer (continued). "Specifically, BRCA1 mutations are strongly associated with basal-like breast cancers, while BRCA2 mutations are more frequently linked to luminal-like breast cancer." (PMID 40867511, 2025). "BRCA1-mutated breast cancer represents a significant subset of cases, primarily defined by its genetic basis and associated clinical outcomes." (PMID 39997609, 2025). "Previous investigations revealed that pathogenic variants in low-penetrance cancer-predisposing genes contribute to breast cancer development in individuals with BRCA1/2 mutations." (PMID 41374957, 2025). "HRD is a pivotal biomarker in oncology, particularly for ovarian and breast cancers, expanding actionable therapeutic targets beyond BRCA1/BRCA2 mutations to enhance patient stratification for PARPi and platinum-based therapies." (PMID 40864792, 2025). "While PARP inhibitors like Olaparib are effective against BRCA1-deficient breast cancers, their efficacy in BRCA1-proficient tumors depends on the functional status of homologous recombination (HR) repair." (PMID 41373774, 2025). "Population-specific differences in the prevalence of BRCA1/2 PVs have been reported in Latin American countries (3.0 to 47.8%), with lower prevalence among unselected breast cancer cases and higher prevalence among individuals at-high-risk of HBOC syndrome." (PMID 40065011, 2025). "In most breast cancer susceptibility genes, Polish common founder mutations are present, including BRCA1, BRCA2, PALB2, and CHEK2, which constitute the majority (>80%) of all mutations detected in these genes in Polish women with breast cancer." (PMID 40649769, 2025). "OPG’s role in the development of BRCA1-mutated breast cancer is due to the known effects that RANKL plays in breast cancer development in patients with BRCA1 mutations." (PMID 39941709, 2025). "Previous studies have shown that triple-negative BRCA1-deficient breast cancer is susceptible to DNA-damaging agents, including platinum-based drugs and poly(ADP-ribose) polymerase (PARP) inhibitors, alone or in combination." (PMID 41226649, 2025). "A subset of breast cancer patients harbor a germline mutation in BRCA1/2 (gBRCA1/2 m), associated with defects in homologous recombination (HR) DNA repair." (PMID 40471518, 2025). "Carriers of pathogenic BRCA1 variants exhibit an estimated cumulative breast cancer risk of approximately 72% by the age of 80, while individuals harboring BRCA2 mutations demonstrate a comparable lifetime risk of around 69%." (PMID 40904409, 2025). "Risk-reducing salpingo-oophorectomy is currently recommended for patients with breast cancer between 35 and 40 years of age for those with a BRCA1 pathogenic variant and between 40 and 45 years for those with a BRCA2 pathogenic variant." (PMID 40070605, 2025). "The estimated overall lifetime risk of breast cancer in BRCA1/2 PV carriers ranges between 50 and 80%." (PMID 40042736, 2025). "This study was conducted to analyze the association between genetic polymorphisms of breast cancer genes 1 (BRCA1) and 2 (BRCA2), which are well known for their association with breast cancer and the development of thyroid cancer." (PMID 40361383, 2025). "Carriers of P/LP variants in BRCA1/2 genes face a complex decision regarding breast cancer risk management." (PMID 40445415, 2025). "Patients with breast cancer with deleterious variants associated with the BRCA1 and BRCA2 genes had a mean age of 43 years (SD = 11.71) and 41 years (SD = 14.62), respectively." (PMID 40259910, 2025). "The new ASCO–Society of Surgical Oncology Guideline recommended testing all newly diagnosed patients with breast cancer for BRCA1/2 mutation ≤65 years and select patients >65 years based on personal history, family history." (PMID 41568010, 2025). "Breast cancer associated with BRCA1 and BRCA2 mutations presents unique therapeutic challenges, traditionally favoring mastectomy due to concerns over recurrence and new primaries." (PMID 41302125, 2025).